IL1B (interleukin 1 beta)
Diseases named in the same sentence as IL1B in open-access papers (continued):
Sharing a sentence is not in itself a finding about the gene and the disease.
infection (continued). "In the present study, the expression of il-8 and il-1β were significantly upregulated in the head kidney and spleen at 30 d after infection, which was accompanied with the increased expression of nf-κb and myd88." (PMID 35052548, 2021). "IL-1β levels were higher in mild disease survivors early after infection, suggesting that innate immunity was briefly stimulated and then arrested in this cohort." (PMID 34372693, 2021). "We observed at 7 d PI, there was a significant effect of the interaction of infection status and feed type on IL1B mRNA levels." (PMID 33652244, 2021). "Mechanistically, MFN2 binds NLRP3 to promote IL-1β secretion after infection with influenza virus and EMCV." (PMID 34482801, 2021). "Unstimulated chondrocytes exhibited various mRNA levels of the different ZC3H12 family members; our RT-PCR and quantitative RT-PCR (qRT-PCR) analyses revealed that Regnase-1 was upregulated by IL-1β treatment or infection of Ad-HIF-2α or Ad-ZIP8." (PMID 33853646, 2021). "F. novicida has served as a prototype for activation of the AIM2 inflammasome and it has been demonstrated that the infection leads to activation of caspase-1 and cleavage of the precursors of IL-1β and IL-18, thereby leading to their secretion." (PMID 35004352, 2021). "Y. enterocolitica and Y. pseudotuberculosis require a functional T3SS to inhibit PGE2 and IL-1β secretion from THP-1 macrophages during infection." (PMID 34319170, 2021). "There were significant decreases in the levels of secreted IL-1β and IL-10 in the fpt mutant-infected BALF samples versus LVS; both fpt mutant strains induced significantly less IL-1β and IL-10 secretion in the lungs at day 6 post-infection versus LVS." (PMID 34202420, 2021). "For Fn U112 infection, cysteine mutations had little impact on NLRP3-dependent IL-1β maturation or the frequency of ASC speck-containing cells." (PMID 34745125, 2021). "IL-1β plays a dual role as it helps to control the infection by the host-inflammatory response, and at the same time permits the entry of luminal content into the serosal compartment of the epithelium to favor inflammation." (PMID 33669494, 2021). "ELISA confirmed that the increased cytokine production (CXCL1, CXCL2, IL-6, and IL-1β) induced by bacterial infection was reverted by AnxA1 treatment in WT mice at 14 h after infection." (PMID 33318141, 2021). "Although essential for resistance to infection, IL-1β also exacerbates damage during chronic diseases and acute injuries." (PMID 33815401, 2021). "IL-1β became detectable at 8 hr, peaked at 18 hr, and remained plateaued thereafter till day 5 post infection in the culture supernatant of human PBMCs infected with live T. marneffei yeasts." (PMID 34912336, 2021). "The IL-1β and IL-18 levels in the LPS + ATP group were significantly higher than those in the control group at 0.5, 3 and 6 h post-infection (P < 0.01)." (PMID 33678162, 2021). "It was found that Rufomycin 4–7 treatment significantly decreased the Mabs-R-induced gene expression of various proinflammatory cytokines and chemokines (Tnfa, Il1b, Il6, Cxcl5, Ccl2, and Ccl4) in BMDMs at 6 h post-infection (hpi)." (PMID 34447358, 2021). "Salmonella typhimurium (S. typhimurium) infection of macrophage induces NLRC4 inflammasome-mediated production of the pro-inflammatory cytokines IL-1β." (PMID 33664876, 2021). "However, reversal of the IL-1β induced gut epithelial damage by Lactobacillus plantarum clearly indicates the existence of synergistic host-microbiota interactions during early pathogenic infection and supports the potential role of these mechanisms as targets for therapeutic intervention." (PMID 33673612, 2021). "In the infected J774.G8 macrophages, as well as in spleens of VACV inoculated mice, the infection with WR-Luc induced a decrease in IL-1β mRNA levels, while WR-IRF3 preserved them." (PMID 34696416, 2021).
infection (continued). "For instance, treatments that focus on systemically negating IL-1β (i.e., anakinra, rilonacept, and canakinumab) have been reported to subsequently result in an escalated peril of infections and are hence deemed improper for oral use." (PMID 34443594, 2021). "Among the five innate immune genes, the elevated il1β, il8, and lysozyme were overlapped in the vaccine-immunized zebrafish and the survival from the infection." (PMID 34950133, 2021). "Another pro-inflammatory cytokine, IL-1β, was strongly positively correlated to cortisol levels during the infection." (PMID 34813597, 2021). "The expression of IL-1β mRNA in the GZ201801-ASFV infection group at 3 h and 12 h increased with the time of infection." (PMID 34835302, 2021). "While increases in IL-1β expression from disc cells upon in vitro infection were observed, levels varied between donors, thus indicating that the capacity of C. acnes infection to strongly induce IL-1β within degenerative discs depends on key host factors." (PMID 33652921, 2021). "IL-1β is a pro-inflammatory cytokine and plays a central role in generating and controlling the immune response in rainbow trout during infection and inflammatory processes." (PMID 34064267, 2021). "Transcription levels of four major proinflammatory cytokines, IL6, IL8, IL1β and TNFα, were examined at different times post infection." (PMID 33712643, 2021). "Infection of wild-type BMDMs with ΔpknF mutant induced a significant production of IL-1β, whereas secretion of IL-1β was completely abrogated in Casp1-/- BMDMs while only partially impaired in Casp11-/- BMDMs." (PMID 34324582, 2021). "TNF-α is secreted by macrophages, natural killer cells, endothelial cells, and fibroblasts, and induces the proinflammatory cytokines IL-1β and IL-6, which are involved in innate immunity in the early stages of infection." (PMID 34884507, 2021). "In TLR2−/− mice, the pyrolysis-related proteins (GSDMD, IL-1α, and IL-1β) upregulated, which showed the immunocompetence in the infection of A. fumigatus." (PMID 34222495, 2021). "In this study we focused on the mechanisms behind inflammasome activation in MDMs and found that HIV can trigger both IL-1β and IL-18 upon infection." (PMID 33861800, 2021). "In the present study, IL-1β was increased at the time of euthanasia, and appeared to be higher during rejection than infection." (PMID 34956220, 2021). "We report that rapid activation of IL‐1β responses in the lung following infection correlates with the development of severe disease during HKx31 H3N2 infection." (PMID 33834544, 2021). "TNF-α and IL-1β are acute-response cytokines appearing early after infection, followed by a more sustained increase in IL-6." (PMID 33995033, 2021). "The IL-1β messenger RNA (mRNA) expression and secretion were significantly increased in a dose-dependent manner during H45 infection." (PMID 34901247, 2021). "We found that IL-1β (p < 0.0001), IL-6 (p < 0.001), and IL-2R (p < 0.0001) raised among patient specimens infected with A. fumigatus; IL-10 was slightly increased after infection (p < 0.05)." (PMID 34222495, 2021). "BMDM cell lysates were collected at 4 hpi and subjected to Western blot analysis to compare the expression levels of pro-IL-1β during infection with Mtb, the ΔpknF mutant and complement ΔpknF::pknF strains (all CDC1551 background)." (PMID 34324582, 2021). "In the systematic immune organ, the expression of il-8 and il-1β in the head kidney and spleen were significantly increased at 30 d after infection." (PMID 35052548, 2021). "Eight hours post-infection, culture supernatant was collected and bioactive IL-1β was measured as in (B)." (PMID 33410748, 2021). "Western blotting combined relative gray values to β-actin data, suggesting that the IL-1β p17 protein expression levels in different infection doses were significantly higher than those in the untreated control (C) group (***p < 0.001)." (PMID 34869071, 2021).
infection (continued). "This was reflected in the induction of an enhanced inflammatory response in the early stages of infection characterized by increases in the numbers of macrophages and neutrophils as well as increases in the levels of IL-1β, IFN-γ, and IL-6." (PMID 34207076, 2021). "We found a marked increase in the release of the pro-inflammatory cytokines TNF-α, IL-1β, and IL-6, after infection, when compared to controls." (PMID 33669494, 2021). "In the serum, only IL-10 and IL-13 were significantly increased, while in urine IFN-γ, TNF-α, IL-13, IL-1β, IL-22, and IL-10 were significantly increased in by infection." (PMID 34662329, 2021). "The levels of IL-1β and IL-18 induced by inflammasome activation were significantly higher in Mint3–/– mice on day 3 of infection." (PMID 33854054, 2021). "This discrepancy is likely due to the route of infection, with IL-1β being important for preventing neuroinvasion or restricting peripheral replication in the nasal mucosa but detrimental once the virus has gained access to the CNS." (PMID 33524073, 2021). "Five days post infection (dpi), the mice administered the different strains showed increased expression of cytokines Il-6 and Il-1β in mesenteric lymph node (MLN) leukocytes (p < 0.05)." (PMID 34785760, 2021). "Compared to peritoneal macrophages from WT mice, cleavage of caspase-1 and expression of IL-1β and IL-18 at both the mRNA and protein levels are reduced in the cells from Aim2-/- mice following infection with MTB." (PMID 33503864, 2021). "Significantly higher levels of proinflammatory cytokines IL-1α, IL-1β, and IL-6 were observed in control mice during infection." (PMID 33514747, 2021). "Infection with SARS-CoV-2 virus causes the body’s immune response in which pro-inflammatory cytokines such as TNF-α, IL-6, IL-1β, IL-2 and IFN-γ are secreted." (PMID 34575258, 2021). "THP-1-defCASP1 cells demonstrated significant reductions in IL-1β expression in comparison to wild-type THP-1 cells upon infection with both early and chronic infection isolates." (PMID 33664232, 2021). "Even an increased expression of IFN-γ and IL-1β was observed in CARD9−/− mice during the early infection phase (3 dpi), indicating the presence of a CARD9-independent activation of cytokine responses." (PMID 34209576, 2021). "In contrast to T. marneffei yeasts, only minimal levels of IL-1β was detected in PBMCs co-cultured with conidia at 5 days post infection, whereas TNF-α production began to increase steadily after 2 days of incubation." (PMID 34912336, 2021). "IL-1β mRNA expression levels in the lung and trachea of group IV were lower compared with other three groups from day 1 to 7 post-infection." (PMID 34988139, 2021). "In conclusion, we found that pathogenic E. coli HPI infection of Yunnan Saba pigs upregulated the expression of NLRP3, caspase-1, IL-1β and IL-18 mRNA, and promoted cell membrane pore formation and nuclear DNA damage in macrophages." (PMID 33678162, 2021). "We injected WT and SIRT3-/- mice intraperitoneally with S. typhimurium and monitored the IL-1β levels in the serum of these mice 6 h after infection." (PMID 33664876, 2021). "More recently, alveolar macrophages were also found to produce IL-1β in vivo upon infection with M. tuberculosis." (PMID 34809460, 2021). "Retrospective analysis of human samples after an Italian CHIKV outbreak revealed an increase in IL-6 during the acute phase of infection, and low levels of IL-1β, TNF-α, IL-12, IL-10, IFN-γ, and IL-5 that increased as disease progressed to the chronic state." (PMID 34106915, 2021). "A member of the CXC chemokine family, Il8/Cxcl8, regulated by Il1b, functions as a chemotactic factor by recruiting specific subsets of leukocytes to sites of inflammation and infection." (PMID 35035387, 2021).
infection (continued). "The results showed that the ability of MS_Rv2650c to stimulate the secretion of cytokines TNF-α, IL-1β, IL-6, and IL-10 was lower than that of MS_Vec after 24 h of infection (paired t-test; P = 0.000006, P = 0.004, P = 0.01, P = 0.00002, respectively)." (PMID 35111145, 2021). "Expression of SOCS-1 during infection correlates with reduced levels of the pro-inflammatory cytokines IL-1β, TNF-α, and IL-6 as well as antimicrobial NO and reactive oxygen species (ROS)." (PMID 33690673, 2021). "Multiple factors contribute to neutrophil recruitment from the circulation to the site of infection, including proinflammatory cytokines (such as IL-1α, IL-1β, TNF-α, and IL-6) and Cxcr2 chemokines (such as Cxcl1, Cxcl2, Cxcl5, and Cxcl8)." (PMID 34011393, 2021). "IL-1β contributes to the generation of both the systemic and local reactions toward infection or injury through the generation of fever, activating lymphocytes and promotion of leukocytic infiltration." (PMID 33995030, 2021). "Among the five innate immune genes, the elevated il1β, il8, and lysozyme are overlapped in the vaccine-immunized zebrafish and the survival from the infection." (PMID 34950133, 2021). "polymorphum and S. gordonii secreted significantly lower levels of IL-1β and IL-6 at 24 h post infection compared with those infected with the co-culture of both species." (PMID 35071038, 2021). "Studies of malaria infection in humans also implicate the role of IL-1β signaling and NF-kB pathways in the innate immune response to infection." (PMID 34399690, 2021). "The expression levels of IFN-α, IFN-β, and IL-1β in the cells at different infection times were higher than those in the control group, especially at 48 hpi." (PMID 33597007, 2021). "This gene regulation of il1β expression levels resembled the known immune response pattern to Fnn infection." (PMID 33435503, 2021). "The activation of NLRP3 inflammasome by microbial stimuli plays a critical role in regulating IL-1β and IL-18 secretion during infection." (PMID 34564598, 2021). "Inflammasomes are activated upon cellular infection or stress and lead to the maturation and release of IL-1β which in turn engages and amplifies innate immune defenses." (PMID 34884681, 2021). "This process causes the secretion of pro-inflammatory cytokines such as IL-1β, which create a heightened inflammatory state, recruiting more CD4 T cells to the sites of inflammation, increasing infection and cell death." (PMID 33542308, 2021). "Previous results indicate that infection by C. gattii induces the production of cytokines related to the Th1 profile more than other species of Cryptococcus, such as IL-1β, TNF-α and IL-6." (PMID 34526536, 2021). "LF pre-infection treatment (unwashed) also significantly decreased the expression of IL1B and IL6 mRNA, whereas pre-infection treatment (washed) left it unchanged." (PMID 33498631, 2021). "In TMEV infection, cytokine balance needs to be tightly controlled, since excessive IL-1β levels have been shown to impair protective immunity and lead to persistent infection in C57BL/6 mice." (PMID 34209576, 2021). "Using in vitro infection models, we confirmed that IL-1β, a crucial innate immune molecule for pathogen control, was very potent against HBV from different genotypes." (PMID 35062269, 2021). "Loss of SETDB2 with coronavirus infection led to increased production of inflammatory cytokines (IL-1β, TNFα, and IL-6) in Mφs via alterations in H3K9me3 at NFkB binding sites on inflammatory gene promoters following infection." (PMID 34479991, 2021). "There is evidence that P2X7R is essential for the secretion of IL-1β in modulating immune responses in infection." (PMID 34987401, 2021). "We found that pro-IL-1β levels in cell lysates are highest in ΔyopB and YopJC172A Y. pseudotuberculosis-infected macrophages, and they are the lowest in wild-type infection, which correlated with secreted IL-1β levels." (PMID 34319170, 2021).
infection (continued). "The increase in its gene expression in relation to the pro-inflammatory mediators IL-1β and IL-8 has been reported as a mechanism of regulation of inflammation and the activation of innate immunity in response to a possible infection." (PMID 34944352, 2021). "The strongest upregulation after infection with MC58 was a 64-fold induction of the gene il1b, while infection of the HIBCPP cells with MC58siaD− resulted in a 77-fold upregulation of the same gene." (PMID 34863201, 2021). "Previous studies have clearly shown that the NLRP3 inflammasome is critical for promoting IL-1β activity by inducing excessive neutrophil recruitment to the site of infection in the skin." (PMID 34011393, 2021). "The transcripts of proinflammatory cytokines (il-1β, il-6, tnfa) and cox2 were significantly (p < 0.05) upregulated at 24 h post-infection (hpi) in IPNv-infected fish." (PMID 34768822, 2021). "IL-1β, IL-6 and IL-8 are commonly upregulated by infection and induce prostaglandin (PG)E2 and PGF2α production to stimulate myometrial contractility and PTB." (PMID 34394055, 2021). "Consistent with a previous study using R. equi strain ATCC 103 in mouse peritoneal macrophages, macrophages infected with R. equi 33701- had greater Il1b expression at 8h post-infection." (PMID 34473814, 2021). "Infection by SARS-CoV-2 induces the release of a proinflammatory cytokine such as IL-1β through activation of TLR2 (toll-like receptor 2), TLR3, or TLR4." (PMID 34306796, 2021). "Serum proinflammatory cytokines (interleukin-6 [IL-6], IL-1β, gamma interferon, and tumor necrosis factor alpha) and the anti-inflammatory cytokine IL-10 were first detected at 12 h postburn with infection and continued to increase until death." (PMID 34152806, 2021). "In contrast, we noticed an EPs 7630-mediated increase in IL-1β and IL-6 levels early post-infection (8 h), with enhanced IL-6 levels also detectable late after infection (48 h)." (PMID 34759825, 2021). "Real-time quantitative PCR was used to detect the mRNA relative expression of pro-inflammatory cytokines, including TNF-α, IL-1β, IL-4, and IL-6 in the supernatant of endothelial cells 48 h after infection with influenza virus." (PMID 34414033, 2021). "Tissue content of TNF-α was not altered, but other cytokines or proinflammatory modulators were increased at different times of infection, namely, IL-1β, MyD88, and RAGE." (PMID 34303703, 2021). "Ptpn11 is the gene that encodes for SHP-2 and it was crucial for the induction of interleukin 1b (IL-1b), IL-6 and IL-23 and responses of the Th17 subset of helper T cells in controlling infection." (PMID 34759909, 2021). "Active caspase-1 cleaves pro-IL-1β and pro-IL-18, cytokines vitally important during infection and inflammation." (PMID 34745125, 2021). "In tissues treated prior to infection, baseline production of IL-1β, IL-22, CCL3, CCL4 and CCL5 varied between BaL- and LAI-infected explants, possibly reflecting virus difference in cell tropism and subsequent CD4 T cell depletion." (PMID 34835109, 2021). "The IFN-γ, IL-1β, and IL-8 cytokines were found to be upregulated in chickens following NE infection as pro-inflammatory cytokines, which lead to tissue inflammation." (PMID 34361680, 2021). "Downregulation of multiple pro-inflammatory genes (CCL5, IL6, IL1B) was accompanied by upregulation of anti-inflammatory TNFAIP3 at 48 h post-infection." (PMID 34759825, 2021). "Despite similar expression changes across all cells following infection, we noted that Il1β was missing from the list of top 10 upregulated genes of the activated Pdpn-KO cells (red dot cluster), but retained in Pdpn-TG cells (red dot cluster)." (PMID 34707599, 2021). "IL-1β and IL-6 enable transmigration of immunocompetent cells to sites of infection by the increased expression of adhesion factors on the surface of the endothelial cells." (PMID 34694623, 2021).